EED (embryonic ectoderm development)
Diseases named in the same sentence as EED in open-access papers (continued):
Sharing a sentence is not in itself a finding about the gene and the disease.
EED also shares sentences with these, for which no sentence is quoted: B-cell non-Hodgkin lymphoma (2 papers); Imagawa-Matsumoto syndrome (2); neurofibromatosis (2); acute lymphoblastic leukemia (1); acute myeloid leukemia (1); asthma (1); BAFopathy (1); benign tumors (1); bowel cancers (1); brain diseases (1); cardiac disease (1); cardiac hypertrophy (1); cardiomyopathy (1); cervical cancer (1); CNS tumors (1); cognitive decline (1); congenital heart disease (1); cryptorchidism (1); dementia (1); diffuse midline glioma (1); endometrial cancer (1); esophageal cancer (1); Graves disease (1); Head and neck tumors (1); intellectual impairment (1); kidney cancer (1); liver fibrosis (1); lung adenocarcinoma (1); lymph node metastasis (1); mantle cell lymphoma (1).
A further 18 diseases each share a sentence with EED in 1 paper.